AGBL2 (AGBL carboxypeptidase 2)
Description:
Metallocarboxypeptidase that mediates deglutamylation of tubulin and non-tubulin target proteins. Catalyzes the removal of polyglutamate side chains present on the gamma-carboxyl group of glutamate residues within the C-terminal tail of tubulin protein. Specifically cleaves tubulin long-side-chains, while it is not able to remove the branching point glutamate. Also catalyzes the removal of polyglutamate residues from the carboxy-terminus of non-tubulin proteins such as MYLK.
Synonyms: CCP2; FLJ23598
Tractability: Small molecule: a high-quality ligand is known. PROTAC: a small molecule that binds it is known.
Target class: Metallo protease; Metallo protease MC clan; Protease; Enzyme; Metallo protease M14B subfamily
Gene: Protein-coding gene on chromosome 11 (47,659,591 to 47,715,389, reverse strand). Ensembl gene ENSG00000165923.
Subcellular location: Cytoplasm, cytosol; Cytoplasm, cytoskeleton, microtubule organizing center, centrosome, centriole; Cytoplasm, cytoskeleton, cilium basal body
Subcellular location (Human Protein Atlas): Basal body; Cytosol; Flagellar centriole; Nucleoli; End piece; Mid piece; Principal piece
Pathways (Reactome):
Metabolism of proteins: Carboxyterminal post-translational modifications of tubulin
Gene Ontology:
Molecular function: protein binding; metallocarboxypeptidase activity; tubulin binding; zinc ion binding
Biological process: proteolysis
Cellular component: centriole; ciliary basal body; cytoplasm; cytosol; microtubule cytoskeleton
Genetic constraint (gnomAD): Loss-of-function variants: 66 observed, 85.78 expected, observed/expected ratio (o/e) 0.77, 90% interval 0.63 to 0.94. The upper end of that interval is the gene's LOEUF score, 0.94, which puts it in group 4 of 6, group 1 being the genes least tolerant of losing a copy. Missense variants: 780 observed, 956.44 expected, observed/expected ratio (o/e) 0.82, 90% interval 0.77 to 0.87. Synonymous variants: 298 observed, 340.96 expected, observed/expected ratio (o/e) 0.87, 90% interval 0.79 to 0.96.
Homologues: Orthologues: chimpanzee AGBL2 (97% identical), macaque AGBL2 (92% identical), dog AGBL2 (82% identical), pig AGBL2 (80% identical), rabbit AGBL2 (78% identical), rat Agbl2 (77% identical), mouse Agbl2 (76% identical), guinea pig AGBL2 (59% identical), tropical clawed frog agbl2 (50% identical), zebrafish agbl2 (46% identical). Paralogues in human: AGBL3 (42% identical), AGTPBP1 (26% identical), AGBL1 (25% identical), AGBL5 (19% identical), AGBL4 (17% identical).
Diseases named in the same sentence as AGBL2 in open-access papers:
AGBL2 is named in the same sentence as 51 diseases in open-access papers, as found by Europe PMC text mining. Sharing a sentence is not in itself a finding about the gene and the disease. The quoted sentences say what the papers report.
breast carcinoma (3 papers, 2014 to 2023). "The underlying genetic mechanism of AGBL2 and its inhibitor latexin in regulating the breast cancer CSC is still unclear and needs further investigation." (PMID 24884516, 2014). "These outcomes suggest that AGBL2 is associated with breast cancer CSC." (PMID 24884516, 2014). "Among the identified genes, three mRNAs, AGBL2, HIST2HAC, and NPHS1, show a significant association with the overall survival of breast cancer patients, with Log-rank test p values of < 0.05." (PMID 38012271, 2023). "Currently, the AGBL2 expression status in breast cancer stem cells (CSC) and the clinical implications for breast cancer are also unclear." (PMID 24884516, 2014). "The outcome demonstrated that AGBL2 plays an important role in breast cancer’s resistance to chemotherapy." (PMID 24884516, 2014). "The methylthiazolyldiphenyl-tetrazolium bromide (MTT) analysis result showed that the proliferation of breast cancer cells was significantly inhibited by AGBL2-siRNA." (PMID 24884516, 2014). "We next examined the effect of AGBL2-siRNA and latexin on invasion in breast cancer cells using the transwell chamber assay." (PMID 24884516, 2014). "Immunohistochemical examination showed that AGBL2 was located in the cytoplasm and membrane of the breast cancers." (PMID 24884516, 2014). "No studies to date, however, have examined the relationship among AGBL2 expression status and breast cancer chemotherapy sensitivity, and the clinical implications of breast cancer." (PMID 24884516, 2014). "In the present study, we try to sort and identify breast cancer stem cells investigate the expression status of AGBL2 in those cells, and evaluate the clinical implications of AGBL2 in breast cancer." (PMID 24884516, 2014). "In the current study, we sorted and identified the breast cancer CSC from clinical specimens, observing that AGBL2 was highly expressed in breast cancer CSC induced to EMT when compared to the control group." (PMID 24884516, 2014). "We investigated the expression status of AGBL2 and its inhibitor latexin in breast cancer stem cells and its clinical implications in order to lay a foundation for managing breast cancer." (PMID 24884516, 2014). "Here, we demonstrated that AGBL2 may also play a role in breast cancer metastasis and may be a potential biomarker for the metastasis and chemotherapy resistance of breast cancer." (PMID 24884516, 2014). "Moreover, drug sensitivity tests showed that a combination treatment of AGBL2-specific siRNA with chemotherapy drugs could significantly increase the apoptosis of breast cancer CSC." (PMID 24884516, 2014). "AGBL2 expression status was detected in CSC and 126 breast cancer specimens by western blot and immunohistochemistry staining." (PMID 24884516, 2014). "We also investigated the relationship between AGBL2 expression and the biological behavior of breast cancer CSC and the clinicopathological characteristics of breast cancer." (PMID 24884516, 2014). "In breast cancer cells RARRES1 was reported to interfere with beta-Catenin and AGBL2 function." (PMID 29169400, 2017). "We found that the expression level of AGBL2 significantly increased in breast cancer stem cells induced to EMT, as opposed to those that were latexin decreased." (PMID 24884516, 2014).
hepatocellular carcinoma (2 papers, 2021 to 2022). A malignant tumor that arises from hepatocytes. "On the other hand, the opposite enzyme, AGBL2, promotes tumorigenesis and cancer progression in breast, ovarian, renal, and hepatocellular carcinoma." (PMID 35008169, 2021). "In hepatocellular carcinoma (HCC), overexpression of the metallocarboxypeptidase AGBL2, an independent prognostic biomarker that promotes HCC cell survival and proliferation, enhanced autophagy and inhibited apoptosis via IRGM up-regulation." (PMID 35699756, 2022).
lymph node metastasis (1 paper, 2014). "The prognostic analysis showed that AGBL2, along with clinical stage, and lymph node metastasis, were significantly associated with a poorer disease-specific survival (P = 0.007, 0.002, and 0.004, respectively)." (PMID 24884516, 2014). "After multivariate analysis, the clinical stage, lymph node metastasis, tumor size, and AGBL2 expression were related to postoperative distant metastasis (P = 0.001, 0.000, 0.003, and 0.031, respectively)." (PMID 24884516, 2014). "Spearman correlation regression analysis showed that AGBL2 expression has a linear correlation to histological stage, lymph node metastasis, and clinical stage (P = 0.036, 0.001, and 0.007, respectively)." (PMID 24884516, 2014). "After Spearman regression correlation analysis, AGBL2 was observed to be related to clinical stage, histological stage, and lymph node metastasis." (PMID 24884516, 2014). "Moreover, AGBL2 protein was found to be related to clinical stage, histological stage, and lymph node metastasis." (PMID 24884516, 2014).
tumor (6 papers, 2014 to 2025). "Including AGBL2 expression in the evaluation, we found a group of patients with 11–15 times higher risk for postoperative tumour progression." (PMID 32307444, 2020). "An association between AGBL2 expression and tumour progression has been described in other types of tumours." (PMID 32307444, 2020). "RARRES1 and AGBL2 expression defines groups of patients at low and high risk of tumour progression and may direct an active surveillance to detect metastasis as early as possible and to apply adjuvant therapy." (PMID 32307444, 2020). "The vast majority of AGBL2-positive cases occurred in the group of tumours with RARRES1 membrane positivity." (PMID 32307444, 2020). "Evaluation of the AGBL2 expression in relation to the clinical–pathological parameters showed significant correlation only with the tumour grade (p < 0.010)." (PMID 32307444, 2020). "Each cell of a given tumour designated as positive case displayed a strong immunostaining with the AGBL2 antibody." (PMID 32307444, 2020). "Out of 454 conventional RCC with membranous RARRES1 expression, 110 tumours showed AGBL2-positive staining as well." (PMID 32307444, 2020). "High expression of ATP/GTP binding protein like 2 (AGBL2) is associated with significantly enhanced survival and proliferation of HCC cells in vitro and tumor growth in vivo." (PMID 33133125, 2020). "Within this group, 110 tumours displayed a strong cytoplasmic AGBL2 expression in addition to membranous RARRES1 expression." (PMID 32307444, 2020). "With all probability, the lack of RARRES1 inhibitor function allows the catalysation of α-tubulin detyrosination by AGBL2 and promotion of tumour progression." (PMID 32307444, 2020). "The four combinations of RARRES1 and AGBL2 expression were significantly correlated with tumour size, grade, necrosis, T stadium and stage as well (Pearson Chi-square test, p < 0.001)." (PMID 32307444, 2020). "Multivariate analysis also revealed that only tumour grade (p ≤ 0.002) correlated with AGBL2 positivity." (PMID 32307444, 2020). "The AGBL2 protein was observed to be expressed significantly higher in cancerous tissues than tumor-adjacent tissues." (PMID 24884516, 2014). "AGBL2 is reported to be involved in tumor epithelial to mesenchymal transition (EMT), but the mechanism by which it operates is still unclear." (PMID 24884516, 2014). "Our observation suggests that RARRES1 may execute distinct biological functions in the same type of tumour depending on its subcellular localisation and co-expression with AGBL2." (PMID 32307444, 2020). "A small group of seven patients with AGBL2-positive and RARRES1-negative tumour displayed a shortest survival by Kaplan–Meier curve estimation (data not shown)." (PMID 32307444, 2020). "Of the group of 237 RARRES1-negative or cytoplasmic positive tumours, 69 showed AGBL2 positivity, whereas 168 ones were negative for AGBL2." (PMID 32307444, 2020). "Cytoplasmic positivity was detected in 180 tumours, whereas 511 ones were negative with the AGBL2 antibody." (PMID 32307444, 2020). "The 344 RARRES1 membrane-positive and AGBL2-negative tumours displayed identical Kaplan–Meier curve as it was seen for membranous RARRES1 alone." (PMID 32307444, 2020). "Using multivariate analysis, only tumour necrosis (p = 0.017) and combination of RARRES1 cytoplasmic/negative and AGBL2-positive/negative immune reaction showed a significant correlation with survival rates." (PMID 32307444, 2020).
cancer (4 papers, 2013 to 2020). A tumor composed of atypical neoplastic, often pleomorphic cells that invade other tissues. "Its downregulation is reported for cancer by interacting with ATP/GTP binding protein-like 2 (AGBL2)." (PMID 23922792, 2013). "In a recent study, AGBL2 was reported as a bridge between cancer stem cell and metastasis." (PMID 24884516, 2014). "The distinct function of RARRES1 and its interaction with AGBL2 and other genes in conventional RCC as well as in other types of cancers remains to be cleared." (PMID 32307444, 2020).
AGBL2 also shares sentences with these, for which no sentence is quoted: Arthritis (16 papers); rheumatoid arthritis (12); infection (4); joint disease (4); rheumatic disorder (4); Autoimmunity (3); synovitis (3); glaucoma (2); spondyloarthritis (2); Stroke (2); Arthralgia (1); asthma (1); bronchiectasis (1); cardiovascular diseases (1); connective tissue disorder (1); cystic fibrosis (1); dermatomyositis (1); essential hypertension (1); fibrosis (1); focal segmental glomerulosclerosis (1); gastric cancer (1); giant cell arteritis (1); heart failure (1); hemolytic-uremic syndrome (1); Hepatitis (1); IgA nephropathy (1); inflammation (1); interstitial lung disease (1); liver cancer (1); membranoproliferative glomerulonephritis type 2 (1).
A further 16 diseases each share a sentence with AGBL2 in 1 paper.